ENSG00000252765
Synonyms: LOC124900440
Gene: Small Cajal body-specific RNA gene on chromosome 1 (101,133,153 to 101,133,339, forward strand). Ensembl gene ENSG00000252765.
Gene Ontology:
Biological process: RNA processing
Cellular component: nucleolus